BCYRN1 (brain cytoplasmic RNA 1)
Diseases named in the same sentence as BCYRN1 in open-access papers (continued):
Sharing a sentence is not in itself a finding about the gene and the disease.
tumor (continued). "Exosomal BCYRN1 overexpression positively correlated with higher tumor stage and lymphatic metastasis of patients with BCa." (PMID 34323412, 2021). "The PTEN/AKT/p21 pathway acts on downstream targets of CUEDC2 to mediate the anti-tumor effect of BCYRN1." (PMID 33995499, 2021). "Our previous study found a significant increase in expression of BCYRN1 in ENKTCL tumor tissue when compared to normal natural killer (NK) cells, especially in those with acquired resistance to asparaginase." (PMID 33391513, 2021). "We found that compared with normal tissues and human intestinal epithelial cells (HIECs), CRC tumour tissues and cell lines had significantly increased BCYRN1 levels." (PMID 32944001, 2020). "Encouragingly, knockdown of BCYRN1 significantly decreased the tumour volume and weight of CRC model mice." (PMID 32944001, 2020). "In order to investigate regulatory roles of BCYRN1 on tumor growth in vivo, we established U251 stable cell line with lentivirus-BCYRN1 to overexpress BCYRN1." (PMID 32978519, 2020). "BCYRN1 expression was closely correlated with tumor depth (P=0.002), lymph node metastasis (P=0.001) and clinical stage (P<0.001) in patients with GC." (PMID 31652309, 2019). "Based on the analysis of our experimental data, this study presents the first evidence that BCYRN1 is upregulated in GC and acts as an oncogene to promote tumor progression and increase EpCAM expression." (PMID 29435146, 2018). "Expression analysis of BCYRN1 in several tumor types has revealed that this lncRNA is expressed in tumor tissues including ovarian cancer samples, but not in the corresponding normal tissues." (PMID 27664137, 2017). "In order to take a step into the mechanism of BCYRN1’s regulating tumor cell metastasis, the RNA and protein levels of representative MMPs, namely MMP9 and MMP13, were respectively measured." (PMID 25866480, 2015). "BCYRN1 can regulate target genes to promote tumor progression by competing with various miRNAs." (PMID 40764575, 2025). "We conducted a meta-analysis of 12 studies including 1,284 cancer patients and 10 distinct cancer types and found that BCYRN1 overexpression in the tumors correlated significantly to poor survival, worse clinical stage, distant tumor metastasis, and advanced tumor T stage with greater invasiveness." (PMID 35874631, 2022). "In light of the emerging evidence that lncRNAs are widely participated in the regulation of cellular signaling pathways in tumor progression, we detected the alteration of essential signaling‐related gene after silencing or overexpressing the BCYRN1 in BCa cells." (PMID 34323412, 2021). "Finally, in vivo xenograft tumor model was constructed to analyze the effect of BCYRN1 on tumor growth and ASP resistance." (PMID 33391513, 2021). "The effect of BCYRN1 on tumor growth and autophagy were confirmed in vivo xenograft model." (PMID 33391513, 2021). "RT-PCR was used to detect the expression level of BCYRN1 in tumour tissues and CRC cell lines." (PMID 32944001, 2020). "In addition, tumorigenesis experiments in a CRC mouse model confirmed that BCYRN1 downregulation effectively inhibited tumour growth." (PMID 32944001, 2020). "Moreover, Yu JH and Chen Y proved that BCYRN1 levels were significantly increased in tumour tissues and cell lines (SW620) of CRC by a series of well-designed in vitro experiments." (PMID 32944001, 2020). "Finally, we explored downstream targets of CUEDC2 essential for BCYRN1-mediated tumor suppressor function." (PMID 32978519, 2020). "Furthermore, we found that BCYRN1 affected the proliferation, apoptosis, migration, invasion abilities in vitro and inhibited the tumor formation in vivo." (PMID 32978519, 2020). "In vivo experiments were performed to evaluate the effect of BCYRN1 on tumour development." (PMID 32944001, 2020).
tumor (continued). "Furthermore, univariate and multivariate Cox regression analyses demonstrated that BCYRN1 expression (P=0.010), tumor depth (P=0.026) and distant metastasis (P<0.001) were independent prognostic factors for overall survival in GC patients." (PMID 31652309, 2019). "In GC, BCYRN1 was increased in GC, and associated with TNM stage and tumor size." (PMID 31652309, 2019). "Subsequently, BCYRN1 was found to function as an oncogenic lncRNA in several types of human tumor." (PMID 31652309, 2019). "We have postulated that GC cells might drive tumor growth through a mechanism involving BCYRN1-mediated cell proliferation." (PMID 29435146, 2018). "Thus, this in vivo study verified that BCYRN1 could lead to resistance of ENKTCL to asparaginase by enhancing autophagy of tumor cells." (PMID 33391513, 2021). "However, a low but detectable level of BCYRN1 was observed in non-tumor lung tissues in this study." (PMID 25866480, 2015). "Conversely, one patient’s serum exosomal BCYRN1 at the second TUR was higher than that at the first TUR, and a residual tumor was observed at the second TUR." (PMID 38892143, 2024). "BCYRN1 is upregulated in colorectal cancer (CRC) tissues, which is related to tumor growth and advanced pathological stages via NPR3 overexpression." (PMID 34489556, 2022). "In this report, BCYRN1 knockdown was shown to suppress HCC proliferative and invasive activity in vitro and tumor growth in vivo." (PMID 35730016, 2022). "In line with our above results, BCYRN1 and BATF overexpression accelerated tumor growth, whereas TM4SF1 silencing had the opposite effect." (PMID 35730016, 2022). "Our results fully elaborate the molecular mechanism in exosomal BCYRN1‐induced synergistical activation of VEGF‐C/VEGFR3 signaling, deepening our knowledge in the mediation of VEGF‐C‐dependent lymphatic metastasis of tumor." (PMID 34323412, 2021). "In consistent with the findings in solid tumors 20, 21, 30, BCYRN1 was found to be a cancer-promoting gene in ENKTCL, which accelerated tumor proliferation, reduced tumor cell apoptosis, and forced cell cycles into S phase." (PMID 33391513, 2021). "We found BCYRN1 was significantly upregulated in GC samples, and its expression was positively correlated with advanced TNM stage (p = 0.0012) and tumor size (p = 0.027)." (PMID 29435146, 2018). "In the present study, we provided the first evidence that BCYRN1 was highly expressed in GC and significantly correlated with high TNM stages and large tumor size." (PMID 29435146, 2018). "In the xenograft assay, we observed a decrease in ki-67 expression in the tumor samples treated with si-BCYRN1, but other markers of proliferation or apoptosis are not examined in this experiment." (PMID 38892143, 2024). "Furthermore, BCYRN1 has been illustrated to be greatly expressed in HCC and its expression was actively connected with tumor-node-metastasis and unfavorable prognosis in HCC patients." (PMID 31920461, 2020). "In addition, we used siRNA, a transient suppressor, in the xenograft assay and did not compare the expression of BCYRN1 in the tumor fragments between the si-control and si-BCYRN1 because 31 days had passed since the assay started." (PMID 38892143, 2024). "It is very likely that the adjacent non-tumor tissues we obtained were so close to the tumor tissue that the adjacent tissues were not entirely separated from the tumor tissues, which may result in the detectable BCYRN1 level." (PMID 25866480, 2015). "Eight patients showed reductions in serum exosomal BCYRN1 at the second TUR and had no residual tumor formation (n = 8, p = 0.0082)." (PMID 38892143, 2024).
cancer (35 papers, 2014 to 2025). A tumor composed of atypical neoplastic, often pleomorphic cells that invade other tissues. "The lncRNA brain cytoplasmic 200 (BC200), also known as brain cytoplasmic RNA1 (BCYRN1), is normally expressed in neurons and is implicated in cancer and neurological diseases." (PMID 35874631, 2022). "We found that high BCYRN1 expression was associated with poor survival prognosis and aggressive clinicopathological characteristics in various cancers, indicating that it is a potential prognostic indicator as well as a therapeutic target." (PMID 35874631, 2022). "BCYRN1 expression was associated with the clinical stage in several cancers." (PMID 35874631, 2022). "Thus, BCYRN1 is a potential diagnostic biomarker and therapeutic target in various cancers, although the underlying mechanisms and clinical significance have to be corroborated further with large-scale, multicenter cohort studies." (PMID 35874631, 2022). "Therefore, further verification of whether BCYRN1 expression is associated with MSI in different types of cancer is warranted." (PMID 35874631, 2022). "Knockdown of the lncRNA BCYRN1 using small interfering RNA (siRNA) reduces cell viability in several types of cancer." (PMID 38892143, 2024). "Our findings are in line with previous reports indicating the prognostic relevance of BCYRN1 in cancer." (PMID 35874631, 2022). "In contrast, BCYRN1 expression was inversely correlated with TMB in six other cancer types, which included COAD, GBM, LGG, LIHC, STAD, and UCEC." (PMID 35874631, 2022). "According to our findings, BCYRN1 is significantly expressed in multiple cancer types, including CHOL, COAD, KIRP, LIHC, LUAD, LUSC, PRAD, and READ." (PMID 35874631, 2022). "BCYRN1 expression was positively correlated with TMB in six cancer types, including BLCA, BRCA, HNSC, LUAD, LUSC, and THYM." (PMID 35874631, 2022). "Further research is needed on pan-cancer cohorts to determine the clinical relevance of BCYRN1 in distinct cancer types." (PMID 35874631, 2022). "Sixth, this paper is an analysis of pan-cancer, but there is heterogeneity between each cancer, and BCYRN1 can be specifically analyzed in separate cancer types in the future." (PMID 35874631, 2022). "BCYRN1 expression was positively correlated with MSI in 8 of the cancer types (DLBC, HNSC, LGG, LIHC, LUAD, LUSC, TGCT, and THCA)." (PMID 35874631, 2022). "Recently, a growing number of studies have revealed that BC200, also known as brain cytoplasmic RNA 1 (BCYRN1), is elevated in a variety of cancer cells, including lung, breast, colorectal, gastric, ovary, and cervix." (PMID 35136029, 2022). "The cancer-related gene BCYRN1 was thoroughly searched in four major English databases: PubMed (n = 53), Web of Science (n = 93), Embase (n = 73), and Cochrane Library (n = 0)." (PMID 35874631, 2022). "We used R software to examine RNA sequencing data in the TCGA database to further investigate the differential expression of BCYRN1 in pan-cancers." (PMID 35874631, 2022). "Previous study reported that BCYRN1 was an oncogenic lncRNA contributing to the progression of various cancers by serving as a crucial microRNA sponge." (PMID 34323412, 2021). "The eIF4A activity is also regulated by the long non-coding (lnc) RNA, human brain cytoplasmic RNA 1 (aka BC200), a 200-nt, predominantly cytoplasmic RNA linked to neurodegeneration and cancer initiation and progression." (PMID 32575790, 2020). "LncRNA Brain Cytoplasmic RNA 1 (BCYRN1) has been certified to modulate cancer cells growth and aggressiveness in several tumors." (PMID 31920461, 2020). "HE staining, immunohistochemical staining and TUNEL staining showed that downregulation of BCYRN1 inhibited Ki-67 expression and promoted cancer cell apoptosis." (PMID 32944001, 2020). "Among numerous lncRNAs, BCYRN1 has been reported to be a critical molecule to regulate cancer cells survival and proliferation." (PMID 31920461, 2020).
cancer (continued). "This coincides with the scarce literature reporting BC200 (also known as BCYRN1) expressed in cancer tissue." (PMID 31646972, 2019). "It has also reported that BCYRN1 is critically involved in the proliferation, apoptosis and metastasis of cancer cells." (PMID 29435146, 2018). "Our study provides new insights regarding cancer progression and highlights the potential utility of BCYRN1 as a novel therapeutic target in GC." (PMID 29435146, 2018). "In accordance to the literature, BCYRN1 (brain cytoplasmic RNA 1) a 200-nucleotide lncRNA, is found highly expressed in some carcinomas of the breast, cervix, oesophagus, lung, ovary, etc., but normally not detectable in the corresponding normal tissues." (PMID 25866480, 2015). "Additionally, abundant BCYRN1 promotes cancer metastasis and progression by adsorbing microRNAs “like a sponge”." (PMID 38892143, 2024). "BCYRN1 was suggested as an oncogenic lncRNA in diverse cancers." (PMID 37143472, 2023). "The results indicate that BCYRN1 expression correlates with TMB in a significant number of cancers." (PMID 35874631, 2022). "Therefore, it is interesting to investigate the relationship between TMB and BCYRN1 expression in different types of cancer." (PMID 35874631, 2022). "The results showed that BCYRN1 expression was significantly correlated with MSI in 14 cancer types." (PMID 35874631, 2022). "Finally, the clinicopathological and prognostic value of BCYRN1 in cancer patients was validated by bioinformatics analysis of cancer databases." (PMID 35874631, 2022). "Despite a number of recent studies indicating that the lncRNA brain cytoplasmic RNA1(BCYRN1) may be a potential predictive biomarker in cancer patients, BCYRN1's prognostic value is still being debated." (PMID 35874631, 2022). "Eight studies including 1,028 cancer patients investigated the link between BCYRN1 levels and OS." (PMID 35874631, 2022). "BCYRN1 expression in cancer and para-cancer tissues was detected by qRT-PCR." (PMID 35874631, 2022). "Using the cBioPortal database, we observed the variation of BCYRN1 in various types of cancer." (PMID 35874631, 2022). "In addition, BCYRN1 expression was inversely correlated with MSI in six other cancer types (ACC, CESC, COAD, KIRC, SARC, and UCEC)." (PMID 35874631, 2022). "BCYRN1, termed as BC200, has been found in a variety of cancers as previous studies." (PMID 32978519, 2020). "Furthermore, we conducted subgroup analyses to look into the relationship between BCYRN1 expression levels and OS based on the cancer type (digestive or other systems), sample size (≥100 or <100 tissues), follow-up time (≥80 or <80 months), and article quality (NOS score ≥8 or≤7)." (PMID 35874631, 2022). "In addition, we demonstrated that BCYRN1 might regulate the expression of EpCAM, which is closely related to carcinogenesis and progression of cancers." (PMID 29435146, 2018). "Brain cytoplasmic RNA 1 (BCYRN1), along non-coding RNA, plays a critical role in various diseases, including some cancers." (PMID 29435146, 2018). "Although BCYRN1 was not identified as a significant correlative feature with POLR3G:POLR3GL gene expression ratios in cancer, it was among the strongest correlative features in primary immune cells, and otherwise ranks among the top cohort with respect to concordant patterns in multiple experiments." (PMID 35637192, 2022).
neurodegenerative disease (2 papers, 2020 to 2021). A disorder of the central nervous system characterized by gradual and progressive loss of neural tissue and neurologic function. "BCYRN1, also known as BC200, was first discovered in 1987 and initial studies mainly focused on its role in brain development and neurodegenerative diseases." (PMID 33391513, 2021). "BCYRN1, also known as brain cytoplasmic 200 (BC200) RNA, is a lncRNA highly expressed in the brain (neuron-specific transcript) in the presence of neurodegenerative diseases." (PMID 32784466, 2020).
BCYRN1 also shares sentences with these, for which no sentence is quoted: ovarian carcinoma (8 papers); colon cancer (4); invasive breast carcinoma (4); Parkinson disease (3); benign tumors (2); breast tumor (2); cognitive disorder (2); glioblastoma (2); Huntington disease (2); neurological disease (2); triple-negative breast carcinoma (2); -dependent (1); adenoma (1); brain cancer (1); ductal carcinoma in situ (1); epilepsy (1); esophageal cancer (1); Fibroadenoma (1); fragile X mental retardation syndrome (1); major depressive disorder (1); multiple sclerosis (1); nasopharyngeal carcinoma (1); Pan (1); parathyroid tumors (1); peripheral neuropathy (1); prostate tumors (1); psychiatric diseases (1); sarcopenia (1); stomach cancer (1); systemic lupus erythematosus (1).
A further 2 diseases each share a sentence with BCYRN1 in 1 paper.